CDK4 (cyclin dependent kinase 4)
Diseases named in the same sentence as CDK4 in open-access papers (continued):
Sharing a sentence is not in itself a finding about the gene and the disease.
lung cancer (continued). "We found that the expression levels of CDK4 were higher in lung cancer tumors compared to those in normal lung tissues." (PMID 21477379, 2011). "The aim of the present study was to analyze the expression of Cyclin-dependent kinase 4 (CDK4) in lung cancer and its correlation with clinicopathologic features." (PMID 21477379, 2011). "In this investigation, we analyzed the expression of CDK4 protein in lung cancer and normal lung tissues by immunohistochemistry." (PMID 21477379, 2011). "In order to clarify the role of CDK4 in the pathogenesis of lung cancer, we explored the correlation of its protein expression with clinicopathologic features of lung cancer patients." (PMID 21477379, 2011). "Multivariate analysis suggested the level of CDK4 expression was an independent prognostic indicator (P < 0.001) for the survival of patients with lung cancer." (PMID 21477379, 2011). "In our study, we found that CDK4 overexpression was significantly correlated with the status of pathology classification, lymph node metastasis, and clinical stage of lung cancer patients." (PMID 21477379, 2011). "Using immunohistochemistry analysis, we analyzed CDK4 protein expression in 89 clinicopathologically characterized lung cancer patients (59 males and 30 females) with ages ranging from 36 to 78 years and compared them to 23 normal lung tissues." (PMID 21477379, 2011). "We found that CDK4 was mainly coexpressed in nucleus and cytoplasm in lung cancer tissues and predominantly expressed in cytoplasm in normal lung tissues." (PMID 21477379, 2011). "In comparison, only 8.7%(2/23) of normal lung samples had highly expressed CDK4 protein, significantly lower than that in the lung cancer samples (P < 0.001)." (PMID 21477379, 2011). "The results indicated that the level of CDK4 expression was an independent prognostic factor for lung cancer (P < 0.001)." (PMID 21477379, 2011). "Further, we presented the evidence that CDK4 protein expression in lung cancer was inversely correlated with patient's overall survival." (PMID 21477379, 2011). "Pharmacological inhibitors of CDK4/6 have become the standard of care in advanced hormone receptor-positive breast cancer and have shown promising results in clinical trials across multiple cancer types, including lung cancer." (PMID 40593477, 2025). "Future studies may explore whether inhibition of TIMM8A-TIMM13 complex can synergizes with conventional cell cycle inhibitors like CDK4/6 inhibitors in lung cancer treatment." (PMID 40918471, 2025). "EMT dependence on CDK-4 (cyclin-dependent kinase 4) has also been described in in vitro models, with promising efficacy for CDK4 inhibitors in reducing tumor volume in a murine model with autochthonous mesenchymal-like lung cancer with a KRASG12D mutation." (PMID 39301544, 2024). "CDK4/6 inhibition is synthetic lethal in SMARCA4-mutant lung cancer." (PMID 39345502, 2024). "However, clinical trials show that the use of CDK4/6 inhibitors, including abemaciclib, are limited for treatment of lung cancer duo to its poor efficacy." (PMID 35814226, 2022). "Additionally, CDK4 expression was significantly reduced in lung cancer cells with PRIM2 knockdown, indicating the cell cycle is suppressed." (PMID 35884433, 2022). "Rk3 could downregulate the expression of cyclin D1 and CDK4, upregulate the expression of P21 protein, and inhibit the proliferation and colony formation of lung cancer cells." (PMID 36569343, 2022). "Moreover, CDK4/6i are currently investigated for treatment of different liquid and solid tumors, including as first‐line treatment for lung cancer patients." (PMID 34985783, 2022). "Notably, the JUNIPER trial in KRASMUT lung cancer has showed that the CDK4/6i Abemaciclib performed better than the EGFR inhibitor Erlotinib, in term of both objective responses and progression free survival (NCT02152631)." (PMID 34654798, 2021).
lung cancer (continued). "In addition, Fascaplysin which is a bis-indole of a marine sponge demonstrated anticancer activity as CDK4 inhibitor in lung cancer cell line." (PMID 33801030, 2021). "Thus, p21 serves as a regulator of CDK4 activity and sensitivity to inhibitors in mesenchymal lung cancer cells." (PMID 34309585, 2021). "Analogous to synthetic lethality, we could potentially broaden the clinical efficacy of CDK4/6i and identify compounds that would synergize with them in lung cancer cell lines." (PMID 34138895, 2021). "Studies on nonsmall cell lung cancer (NSCLC) have shown that the high expression of YTHDF1 can promote the development of tumors by promoting protein translation of cyclin E-associated kinase 2 (CDK2), cyclin-dependent kinase 4 (CDK4) and cyclin D1 mRNAs." (PMID 33692959, 2021). "Mesenchymal lung cancer cells exhibit increased dependency on CDK4 for growth." (PMID 34309585, 2021). "Therefore, our findings revealed that licorice inhibit the expression of CDK4-Cyclin D1 complex would be critically important for prevention and treatment of lung cancers." (PMID 34641869, 2021). "Myc- FAM136A- CDK4/6 might be a new signaling pathway regulation axis in lung cancer, but this has yet to be demonstrated." (PMID 32098576, 2020). "It regulates p21 and CDK4 expression thereby inducing apoptosis of lung cancer cells." (PMID 32711579, 2020). "CDK4 was reported to be upregulated in lung cancer tissues, and high expression of CDK4 was closely correlated with pathology classification, lymph node metastasis and clinical stage of lung cancer patients." (PMID 33292236, 2020). "CDK4 overexpression in lung cancer may accelerate tumour progression and leads to an overall shorter survival time in lung cancer patients." (PMID 32104498, 2020). "Exposure of HCT116 and SW480 colorectal cancer cells to patchouli alcohol activated p21 expression and inhibited the expression of cyclin D1 and CDK4 and induced cell apoptosis and cell cycle arrest in A549 lung cancer cells in vitro and in vivo via the EGFR-MAPK pathway." (PMID 32963578, 2020). "Since a synthetic lethal interaction has been reported between KRAS mutants and CDK4, we asked whether expression of cyclin D1 and CDK4 might be associated with the KRAS mutation in lung cancer patients." (PMID 32104498, 2020). "A study of the mechanisms indicated that BOS-102 could significantly block cell proliferation in human A549 lung cancer cells and effectively induce G0/G1 cell cycle arrest via targeting cyclin D1 and cyclin-dependent kinase 4 (CDK4)." (PMID 29370087, 2018). "Fascaplysin has stronger anti-cancer effects than other CDK4 inhibitors on lung cancer cells that are wild-type or null for Rb, indicating that unknown target molecules might be involved in the antitumor activity of fascaplysin." (PMID 30322180, 2018). "Cyclin D1 is the main regulator of CDK4/6 and is upregulated in most lung cancer cells." (PMID 29764507, 2018). "In lung cancer cell lines and genetically-engineered mouse models, depletion, genetic ablation or inhibition of CDK4/6 has demonstrated synthetic lethality in KRAS-mutant, but not wild-type backgrounds, suggesting the therapeutic relevance of selective CDK4/6 inhibition." (PMID 30167080, 2018). "Furthermore, preclinical data suggest activity of CDK inhibitors in lung cancer xenograft models, and therefore, CDK4/6 inhibitors are currently under investigation for the treatment of advanced lung cancers." (PMID 28396848, 2017). "The observed positive correlation supports future testing of this hypothesis to examine a potential therapeutic strategy for treating lung cancer patients harbouring STK11 alterations with a CDK4 inhibitor such as palbociclib." (PMID 28205554, 2017). "We investigated whether a cyclin D kinase 4/6 (CDK4/6) inhibitor, PD 0332991, could reverse EGFR-TKI resistance in human lung cancer cells and explored the underlying mechanisms." (PMID 27825114, 2016).
lung cancer (continued). "Likewise, the CDK4 R24C point mutation confers selective growth advantage by causing loss of CDK4 binding to p16INK4a, and consequently constitutive activation of CDK4 in familial melanoma and in a subset of lung cancers and lymphomas." (PMID 25625291, 2015). "Dysregulation of the p16INK4a/CDK4/CyclinD pathway is equally frequent in lung cancers." (PMID 25625291, 2015). "CDK4/Cyclin D1 overexpression is an indicator of prognosis in human primary lung carcinoma." (PMID 25625291, 2015). "Our results indicate that overexpression of cyclin D1 and CDK4 in lung cancer tissues may partially result from the underexpression of miR-545." (PMID 24505359, 2014). "CDK4 is a protein kinase of the CDK family that is important for cell cycle G1 phase progression, and its expression pattern is associated with clinical pathology parameters of lung cancer patients." (PMID 21477379, 2011). "Our results suggested CDK4 overexpression in lung cancer may accelerate tumor progression by promoting cell growth." (PMID 21477379, 2011). "Furthermore, we observed that in 50.6% (45/89) of lung cancer samples, CDK4 protein was highly expressed." (PMID 21477379, 2011). "In summary, our results provide evidence that CDK4 may be involved in the development of lung cancer." (PMID 21477379, 2011). "Finally, our work is the first to present that CDK4 mediates cell cycle progression by regulating the expression of p21 expression in lung cancer." (PMID 21477379, 2011). "Furthermore, the involvement of CDK4-mediated cell cycle progression and its molecular basis were investigated in the pathogenesis of lung cancer." (PMID 21477379, 2011). "Furthermore, we presented evidence that CDK4 in nucleus and total protein levels was overexpressed in lung cancer tissues compared to normal lung tissues." (PMID 21477379, 2011). "To determine whether CDK4 is an independent prognostic factor for lung cancer, we performed multivariate analysis of CDK4 expression adjusted for the same parameters." (PMID 21477379, 2011). "In addition, overexpression of CDK4 was positively related to advanced disease status of lung cancer patients." (PMID 21477379, 2011). "We examined the effect of decreased CDK4 expression on lung cancer cell growth in vivo." (PMID 21477379, 2011). "Overexpression of CDK4 has been described in many tumors, including lung cancer." (PMID 21477379, 2011). "Our results suggest that CDK4 may be involved in the development of lung cancer by antagonizing the effect of p21." (PMID 21477379, 2011). "Our previous work identified the inhibition of glutaminase as a metabolism-based strategy to combine with CDK4/6 targeting therapy, a combination subsequently corroborated as effective to overcome CDK4/6i resistance in esophageal squamous cell carcinoma and lung cancer." (PMID 40696167, 2025). "Finally, besides CRC, upregulated YAP1, cyclin D, CDK4/6, and DUB3 are similarly implicated in various cancers such as lung cancer and ovarian cancers, thus the implication of this axis in these malignancies should be investigated by further preclinical and clinical study." (PMID 39968498, 2025). "Therefore, further exploration of the mechanisms underlying CDK6 overexpression and the development of combination strategies to downregulate CDK6 expression have significant clinical value for overcoming CDK4/6i resistance in hormone-independent cancers, such as lung cancer." (PMID 37452037, 2023). "Therefore, we propose that FBXO22 controls the cell cycle by regulating substrate protein levels, which we confirmed in the lung cancer cell line A549: overexpression of FBXO22 increased the expression of cyclin-dependent kinase 4 (CDK4) and promoted cell proliferation." (PMID 35141150, 2021).
lung cancer (continued). "Accumulating studies revealed that aberrant CDK4 could participate in many cellular pathways associated with malignancies, including the PI3K/Akt signalling pathway in lung cancer, the Wnt/β‐catenin signalling pathway in BC and the JAK‐STAT signalling pathway in gastric cancer." (PMID 33452764, 2021). "CDK4/6 might play a vital role in the proliferation, migration, and apoptosis of lung cancer cells." (PMID 32098576, 2020). "Therefore, we assume that Myc- FAM136A- CDK4/6 might be a new signaling pathway regulation axis in lung cancer, but this hypothesis needs more evidence." (PMID 32098576, 2020). "Thus, loss of STK11 in lung cancer cells may lead to enhanced sensitivity to palbociclib, demonstrating an STK11-loss evoked enhanced-dependency of cells on CDK4." (PMID 28205554, 2017). "Moreover, compound 5i could induce G1 cell cycle arrest and autophagy in lung cancer cells through up-regulating P27, down-regulating CDK4 and cyclinD1 and attenuating PI3K/Akt/mTOR pathway." (PMID 27786281, 2016). "Furthermore, overexpression of CDK4 has been observed in many tumor types, including oral squamous cell carcinoma, pancreatic endocrine tumors, lung cancer, and nasopharyngeal carcinoma, suggesting that CDK4 is a significant factor in promoting the initiation and development of tumors." (PMID 24751144, 2014). "Furthermore, overexpression of CDK4 has been showed in many tumor types, including oral squamous cell carcinoma, pancreatic endocrine tumors, lung cancer, and nasopharyngeal carcinoma, suggesting that CDK4 is a key factor in promoting the initiation and development of tumors." (PMID 21477379, 2011). "Furthermore, we also demonstrated that CDK4 could serve as a potential independent prognostic factor for lung cancer patients." (PMID 21477379, 2011). "In addition, high levels of CDK4 protein were positively correlated with the status of pathology classification (P = 0.047), lymph node metastasis (P = 0.007), and clinical stage (P = 0.004) of lung cancer patients." (PMID 21477379, 2011). "Functionally, OCS selectively downregulated phosphorylation of kinase clients (e.g., CDK4, P-AKT473, P-ERK1/2) and induced apoptosis in A549 lung cancer cells (IC50 ≈ 22.7 μM)." (PMID 40491798, 2025). "Reduced levels of CDK4, CDK6, and pRB coincided with the elevated levels of p21 after SAHA treatment in lung cancer cells confirmed cell cycle arrest, as shown in Western blot analysis." (PMID 40941018, 2025). "Recent work by the Ruscetti group highlights how the combination of CDK4/6 and MEK inhibitors synergistically and favorably alters the tumor microenvironment of Ras-driven lung cancer and pancreatic ductal adenocarcinoma (PDAC)." (PMID 40723291, 2025). "A study demonstrated that hyperoside exerts an inhibitory effect on the lung cancer cell line A549, with its mechanism involving the suppression of cyclin D1 (CCND1) and cyclin-dependent kinase 4/6 (CDK4/CDK6) expression." (PMID 40098612, 2025). "CDK4/6 inhibitors can trigger ICAM1 to coordinate anti-tumor immune responses and make LKB1 mutant lung cancer sensitive to immunotherapy." (PMID 40568576, 2025). "Targeted therapeutic strategies aimed at these critical nodes, such as inhibiting CDK4 or cyclin D1 activity or restoring RB1 function, are expected to offer new therapeutic avenues for lung cancer patients." (PMID 40568194, 2025). "In a separate study involving RB‐mediated senescent lung cancer cells induced by MAPK and CDK4/6 inhibitors, increased expression of CCL2, CCL4, CCL5, CXCL10 and CXCL1 was observed." (PMID 39270064, 2024). "Transcriptome expression analysis from the GEPIA showed lung cancer tissues also exhibited higher NRAS, Cdc25a, CDK4, and γ-H2A.X expression." (PMID 38778121, 2024). "Treatment with MH led to the dose-dependent inhibition of CDK4/6 and CDC2 expression in both drug-sensitive (A549 and H1299) and drug-resistant (A549-TR) lung cancer cells." (PMID 39518013, 2024).
lung cancer (continued). "In this study, after reducing RACGAP1 expression in lung cancer cells A549 and H1975 by using si technique, flow cytometry revealed that the expression of cell cycle-related proteins CDK2 and CDK4 was reduced." (PMID 38167018, 2024). "The study evidenced that this compound induced apoptosis of the lung cancer cells and cell cycle arrest in the G0/G1 phase by reducing the expression of cyclin D1 and CDK4 (cyclin-dependent kinase 4)." (PMID 37298856, 2023). "Leveraging mouse models of Kras-mutant lung cancer, inducing cellular senescence by combined MEK and CDK4/6 inhibition provokes SASP-dependent and natural killer (NK) cell surveillance program and tumor cell death." (PMID 37591827, 2023). "It was also previously reported that the inhibition of MAPK and CDK4/6 induces cell cycle arrest and senescence in KRAS-mutant lung cancer cells." (PMID 35614034, 2022). "Inhibition of both MEK and CDK4/6 by palbociclib induced responses in mutant KRAS colorectal and lung cancer models." (PMID 36048281, 2022). "In addition, RB1 mutations combined with CDK4/6 deficiency had synthetic viable effect in lung cancer cells, which indicates that the lung cancer patients with RB1 mutations could not be suggested to use Palbociclib." (PMID 36180906, 2022). "We found increased mRNA levels of p21 and a significant decrease in cell cycle-promoting proteins such as CDK2, CDK4, cyclin E1, and cyclin D1, suggesting a possible tumor-suppressing role of LCK in liver and lung cancers." (PMID 36430477, 2022). "In H1299 lung cancer and endometrial cancer cell lines, garcinol application resulted in cell cycle arrest and a marked decrease in cyclin-dependent kinase 2 (CDK2) and cyclin-dependent kinase 4 (CDK4) expression." (PMID 33799504, 2021). "This was confirmed in nonsmall cell lung cancer A549 cells, where FBXO22 overexpression enhanced cyclin-dependent kinase 4 (CDK4) protein levels and promoted cell proliferation." (PMID 35141150, 2021). "Parallel evolution has been shown in a variety of neoplasms, including lung cancers involving genetic alterations in the MUC1, CDK4, CHD8, and NKX2‐1 genes." (PMID 32333643, 2020). "For instance, the circ-HIPK3 transcript acts as a microRNA-124 (miR-124) sponge and regulates the expression of miR-124 mRNA targets, including SphK1, CDK4, and STAT3, in lung cancer cells." (PMID 32692763, 2020). "ART restricted proliferation of lung cancer cells in the G0/G1 phase by decreasing Cyclin D1, Cyclin E, CDK2, and CDK4 expression." (PMID 33316936, 2020). "Expression of cell cycle regulatory proteins CDK4, CDK6, and cyclin D1 was significantly decreased in ApoE knockdown lung cancer cells." (PMID 31275318, 2019). "KLF8 regulated the expression of the cell cycle regulators P21 and CDK4 in a JMJD2A-dependent manner and JMJD2A knockdown significantly blocked the functions of KLF8 in regulating cell cycle and proliferation of lung cancer cells." (PMID 31624471, 2019). "We determined the CDK1, CDK4 and CDK6 mRNA expression alterations due to transfection with miR-143 and/or miR-506 in A549 lung cancer cells using quantitative real-time PCR (qRT-PCR)." (PMID 30002440, 2018). "Based on OncoPPi-derived STK11-CDK4 connectivity, we observe enhanced sensitivity of STK11-silenced lung cancer cells to the FDA-approved CDK4 inhibitor palbociclib." (PMID 28205554, 2017).